INS (insulin)
Diseases named in the same sentence as INS in open-access papers (continued):
Sharing a sentence is not in itself a finding about the gene and the disease.
diabetes (continued). "Given the notable similarities between ILP-Ap04 and human insulin, along with its hypoglycemic effects observed in zebrafish diabetes models, it is plausible to suggest that ILP-Ap04 might also interact with the human insulin receptor." (PMID 38535452, 2024). "Insulin is an important therapeutic agent for patients with type 1 and type 2 diabetes mellitus." (PMID 38884020, 2024). "In the early stages of diabetes, the body may retain some residual insulin production, particularly in Type 2 diabetes, which aids in regulating blood sugar levels." (PMID 38800154, 2024). "Early studies suggest that selenium plays a role in insulin mimic and anti-diabetes." (PMID 37145256, 2024). "In addition to a healthy diet and increased physical activity, patients with diabetes mellitus are often prescribed oral glucose-lowering drugs (OGLDs) and/or insulin or injectable agents to achieve glycaemic control." (PMID 38694587, 2024). "Obesity, which can decrease internal sensitivity to insulin, may induce impaired glucose tolerance and even diabetes." (PMID 39036051, 2024). "In older people with diabetes, insulin dose errors, including missed insulin or double doses, are common and may account for suboptimal glycaemic management or unexplained glucose variability." (PMID 39138689, 2024). "In diabetes, there is a disruption and malfunction in insulin regulation." (PMID 38542928, 2024). "Thus, teplizumab has consistently showed improved endogenous insulin production when given during stage 2 or stage 3 diabetes." (PMID 39568817, 2024). "Furthermore, a study conducted in the Kingdom of Saudi Arabia (KSA) showed that compliance rates for individuals with diabetes range from 60% to 80% for insulin and from 65% to 85% for oral antidiabetic drugs." (PMID 39292676, 2024). "Youth with T1D face additional stressors during adolescence including, but not limited to, learning to independently manage their T1D regimen (e.g., monitoring blood glucose levels, carbohydrate counting, and administering insulin) and perceived stigma related to having diabetes." (PMID 39014980, 2024). "Diabetes management tools are essential for monitoring glucose, insulin levels, and meal ingestion." (PMID 38378741, 2024). "The significant improvements observed in these parameters suggest that CPCM may be an effective intervention for enhancing glycemic control, promoting insulin secretion, and improving overall metabolic health in individuals with diabetes." (PMID 39840100, 2024). "This capability makes them particularly promising for the development of glucose-responsive systems for insulin delivery, which could revolutionize diabetes management." (PMID 39188756, 2024). "Diabetes is a metabolic disease characterized by chronic hyperglycemia with impairment of carbohydrate metabolism caused by partial or non-secretion of insulin." (PMID 38305822, 2024). "In a clinical study in patients, serum Put has been found significantly elevated in patients with type 2 diabetes (T2D) compared to those without diabetes and Spm was significantly associated with fasting insulin levels." (PMID 38918813, 2024). "In 2010, the MD‐Logic algorithm using fuzzy logic models to drive insulin delivery was piloted; instead of using mathematical models, insulin delivery is altered based on predicted decisions that would be made by diabetes clinicians in response to detected rtCGM metrics." (PMID 39291355, 2024). "(E)-5-hydroxy-7-methoxy-3-(2′-hydroxybenzyl)-4-chromanone (HM-chromanone), a sapanin homoisoflavonoid that derived from Portulaca oleracea L., has an extensively potential in promoting insulin secretion and anti-diabetes effect of a substance isolated from TCM." (PMID 38799166, 2024). "Considering their effect on pBMI, they could play a role in insulin signaling, glucose homeostasis, mitochondrial metabolism, and inflammatory responses, at least in women with type 1 diabetes mellitus." (PMID 38474283, 2024).
diabetes (continued). "We performed logistic regression analysis with adjustment for age, menopausal age, income, urban area, education, insulin use, body mass index, hypertension, diabetes mellitus, dyslipidemia, high alcohol intake, smoking, exercise, oral contraceptive use, and hormonal therapy use." (PMID 38613076, 2024). "Korean diabetic patients are known to have low insulin secretion ability, but as the number of overweight and obese diabetic patients increases, insulin resistance is considered a more prominent pathophysiology of diabetes." (PMID 39436903, 2024). "When comparing different treatment groups, a higher percentage of individuals in the insulin group were also on high BP (74.6%) and cholesterol (56.8%) medications, indicating a higher prevalence of comorbidities or an advanced stage of diabetes requiring mixed (insulin and tablet) treatment." (PMID 39587498, 2024). "Additionally, our study excluded individuals taking insulin or other medications for diabetes, so the conclusions cannot be generalized to the population of patients with advanced diabetes." (PMID 38997689, 2024). "Similarly, some studies were unable to establish a causal relationship between changes in osteocalcin and incident diabetes and insulin levels." (PMID 39872315, 2024). "The 5:2 diet could reduce fasting serum insulin acutely during a two-day fast and moderately stimulate the release of adiponectin by adipose tissues, which improved insulin sensitivity and lowered the risks of developing cancer, heart disease, or diabetes." (PMID 38337642, 2024). "We demonstrate that RFX6 haploinsufficiency does not affect beta cell number or insulin content but does impair function, predisposing carriers to diabetes." (PMID 38743124, 2024). "Also, silybin enhances the sensitivity to insulin of insulin-dependent cells like hepatocytes and myocytes and has a hypoglycaemic effect in patients with diabetes mellitus type 2." (PMID 38953241, 2024). "The American Diabetes Association recommends parents and caregivers to educate themselves about T1DM; attend diabetes education classes; and learn insulin administration, blood glucose interpretation, hypoglycemia or hyperglycemia signs, ketoacidosis treatment, and carbohydrate counting." (PMID 39658013, 2024). "The adipose-derived insulin-sensitizing factor adipolin-related C1q/TNF-related Protein-12 (CTRP12) is such a newly described adipokine with anti-inflammatory and insulin-sensitive effects that can counteract complications involved with obesity, inflammation, as well as diabetes." (PMID 39308032, 2024). "Overexpression of TGFB1 under a rat insulin promoter reduces the risk of diabetes in T1D susceptible nonobese diabetic mice." (PMID 39464889, 2024). "Several studies indicate that vasopressin cooperates with insulin in several planes and may play the role of a link in the development of hypertension and diabetes mellitus." (PMID 39769071, 2024). "Overexpression of these proteins may play significant roles in insulin resistance and the development of vasculopathy during the onset of diabetes." (PMID 39206042, 2024). "Approximately one-fourth of the respondents have highlighted that reducing the focus on diabetes treatment (Q3.7, 22% - n = 17) and having less liability (Q3.8, 29% - n = 22) in insulin dosage calculation would be another significant advantage of using such medical devices." (PMID 39376804, 2024). "Diligent efforts are required for daily diabetes care to ensure optimal glycemic control, including testing blood glucose multiple times daily, determining appropriate doses of insulin, and administering it with utmost vigilance, with rapid reactions to low and high readings." (PMID 40303263, 2023). "Women, older people, those with lower education, higher BMI groups and those with longer disease durations, those with a history of forgoing treatment, and those whose main treatment was based on insulin injection were more likely to have diabetes complications." (PMID 36761031, 2023).
diabetes (continued). "This suggests that early metabolic alterations in insulin sensitivity and adipose tissue function rather than overt diabetes and hyperglycemia are linked to changes in the GH system." (PMID 36959287, 2023). "If diabetes is induced by COVID-19, it likely requires an interplay of multiple conditions such as stress- and/or steroid-related hyperglycemia combined with virally induced disruptions in glucose disposal and insulin secretion." (PMID 36741600, 2023). "They acknowledged that one of the most important challenges during Kermanshah, Varzaghan, Ahar, and Haris earthquakes was the scarcity of medications particularly diabetes medications including insulin and chronic respiratory disease medications including the spray." (PMID 36871176, 2023). "Diabetes mellitus was defined as a fasting plasma glucose level of ≥ 7.0 mmol/L, a 2-h post-loaded glucose level of ≥ 11.1 mmol/L, HbA1c ≥ 6.5%, and/or the current use of insulin or oral glucose-lowering agents." (PMID 37821847, 2023). "Patients with Type 2 diabetes Mellitus may inadequately control on oral antidiabetic drugs when they are put on twelve weeks of insulin glargine therapy having hepatic fat reduction on MRS by 12.6 % to 9.9% with an improvement in HbA1c from 7.9% to 7.2%." (PMID 38223606, 2023). "After adjusting for age, sex, SBP, drinking status, duration of diabetes, HbA1c, insulin usage, axial length, and image quality score, a lower baseline average pRNFL thickness was significantly associated with a higher CVD risk (OR = 1.35, 95% CI :1.11–1.65, p = 0.003)." (PMID 36653845, 2023). "Activation of PPARα by fibrates successfully reduces TAG and increases HDL levels, while activation of PPARγ by thiazolidinediones (TZDs)/glitazones may improve insulin sensitivity in patients with diabetes mellitus." (PMID 36834808, 2023). "Sub-sequentially this may lead to a decrease of circulating oxygen, insulin and glucose which could catalyze the progression of metabolic abnormalities like diabetes." (PMID 37633936, 2023). "Higher insulin and/or C-peptide levels, indicative of insulin resistance, are linked to increased recurrence and mortality risks in early-stage BC, irrespective of diabetes." (PMID 37893423, 2023). "While emphasizing telemedicine's effectiveness in managing FBS levels, a critical aspect of diabetes control, among patients utilizing insulin therapy in primary care, the study underscores the need for more extensive, large-scale research to fully comprehend its impact on diabetes management." (PMID 38077677, 2023). "In addition to its canonical role in skeletal function, vitamin D modulates insulin secretion and action in diabetes." (PMID 37111216, 2023). "The reason might be they are frequently engaged with their farm work and unable to control their blood glucose level, unable to maintain a healthy diet which is recommended for diabetes, and hesitant of taking their diabetic agent or insulin on time." (PMID 36643789, 2023). "Epidemiological analysis showed a negative relationship between serum iron (frozen) and Fins, indicating that IO might affect insulin secretion and eventually induce diabetes." (PMID 37344885, 2023). "Similarly, ebselen, a GPx mimic, also improved insulin sensitivity, preserved pancreatic β-cell function in diabetic rodents and prevented diabetes-related atherosclerosis and renal damage." (PMID 37237860, 2023). "Our finding of sustained higher levels of anxiety in women with GDM requiring insulin has important implications for their pregnancy outcomes as anxiety has been associated with poor glycaemic control in non-pregnant populations with diabetes." (PMID 36733299, 2023). "We have come a long way in the management of diabetes—from herbs, chemicals and extreme starvation diets before the advent of insulin to potent oral agents and injectables which improve glycemia, and in the case of the SGLT2i and the GLP-1RA, provide robust cardio-renal protection as well." (PMID 36845885, 2023).
diabetes (continued). "However, the administration of WJMSC-CM and insulin significantly decreased the expression level of TNF-ɑ mRNA compared to the untreated diabetes group (P < 0.01)." (PMID 37081849, 2023). "Thus, 21% thought that corona is transmitted by insect bites and 30.3% thought that corona is transmitted to a person with diabetes through an insulin injection needle." (PMID 36805712, 2023). "Skeletal muscle tissue is an insulin-dependent organ, and its insulin resistance triggers diabetes." (PMID 37929025, 2023). "Since Rab26 is involved in insulin secretion, the expression of Rab26 may be related to diabetes mellitus." (PMID 37289842, 2023). "The diabetes relapsed at age 9, and treatment with insulin was prescribed." (PMID 36836406, 2023). "Conversely, around 1 in 3 of those with type 1 diabetes defined by the development of severe insulin deficiency are treated without insulin at diagnosis, with 47% of these individuals still reporting type 2 diabetes at 17 years of diabetes duration." (PMID 37728732, 2023). "In addition, the vast majority preferred to receive advice about insulin dose changes, with lower proportions seeking advice about diabetes skills and behaviors, diabetes technology use, and emotional support related to diabetes care." (PMID 36817610, 2023). "Therefore, maintaining GPC-4 serum levels in people with IR or diabetes mellitus can reduce their need for insulin therapy." (PMID 37151681, 2023). "Insulin plays an important role in the treatment of diabetes mellitus." (PMID 37501783, 2023). "For patients and/or caregivers with low levels of education or mathematical skills, the diabetes care team should try as much as possible to overcome these barriers, and modify diabetes education to enable them to calculate the carbohydrate content and insulin doses accurately under supervision." (PMID 40303263, 2023). "Insulin pump therapy can reduce the number of daily injections required for insulin delivery and may eliminate the need for frequent fingerstick blood glucose monitoring, thereby reducing the burden of diabetes management and improving the QoL." (PMID 37485197, 2023). "Primary outcomes were time to optimal insulin dose (number of days needed to achieve glycemic control), insulin adherence, and change in composite survey scores measuring diabetes-related emotional distress and attitudes toward health technology and medication adherence." (PMID 38039007, 2023). "Clinical diabetes-related outcomes {body mass index (BMI), hemoglobin A1c (hbA1c), daily insulin dose, diabetic ketoacidosis (DKA), hypoglycemia, number of hospital admissions, number of hospital days} were analyzed, stratified by age groups (≤ 25 years vs. > 25 years)." (PMID 36707607, 2023). "During this period, the individual’s diabetes may improve, and the patient may require less insulin than the first few days after diagnosis." (PMID 37446104, 2023). "Moreover, this modification can be produced via GLA, because it is responsible for insulin sensitivity in rat muscle tissue and ultimately for diabetes suppression." (PMID 37447270, 2023). "DEBs are harmful to patients with diabetes, especially those who are on insulin." (PMID 37752601, 2023). "Therefore, this study is meaningful to observe the change in diabetes status and changes in serum glucose and insulin in kidney transplant patients who have already been diagnosed with diabetes." (PMID 37424863, 2023). "Advanced diabetes technologies, e.g., automated insulin delivery (AID), may reduce the burden and improve treatment outcomes." (PMID 38129890, 2023). "The advantages of pioglitazone therapy, which include better sensitivity to insulin and management of diabetes mellitus, are weighed against its side effects, which include increased body weight, retention of fluids, a decrease in bone density, and a potential rise in bladder cancer." (PMID 38186528, 2023).
diabetes (continued). "This supports the idea that hyperglycaemia may contribute to macrovascular complications in diabetes by impairing certain branches of insulin signalling pathways." (PMID 38139295, 2023). "Unfortunately, despite the ongoing saga of skin reactions towards diabetes medical devices, it has already been reported that the relatively new insulin pump system YpsoPump (Ypsomed, Burgdorf, Switzerland) also contains IBOA, and the first cases of ACD elicited by this device are known." (PMID 37445875, 2023). "Participants in both studies understood diabetes through the body’s use of insulin." (PMID 36791113, 2023). "The FPDR, covering approximately 90% of newly diagnosed diabetic individuals aged ≤15 years in Finland starting from 2002, includes data on diabetes-associated HLA genotypes and AAB data (ICA, and autoantibodies against insulin, GAD, islet antigen 2 and zinc transporter 8) at diagnosis." (PMID 36418577, 2023). "B cell recognition of insulin is necessary for NOD mice to develop diabetes; NOD mice that harbor an increased frequency of anti-insulin B cells due to the VH125 BCR transgene develop accelerated T1D, whereas transgenic mice lacking this critical B cell specificity are protected." (PMID 37261716, 2023). "Due to a lack of coding in the dataset, we were unable to report more nuanced and specific metrics such as duration of diabetes, total daily dose of insulin, percentage time in range and reason for starting adjunctive therapy, all of which are clinically relevant." (PMID 37505282, 2023). "Lastly, in individuals experiencing a biochemical diabetes due to leprosy related corticosteroids, an assessment of diabetes control including duration of illness, therapeutics used, and insulin status will also be carried out to monitor any changes throughout the trial." (PMID 37469546, 2023). "Nevertheless, the varied use of each diabetes medication class in the diabetes subgroup at baseline (including approximately 50% of patients on insulin) suggests that this subgroup represents a spectrum of disease progression and management needs within type 2 diabetes." (PMID 37592272, 2023). "Regarding the association between medication adherence and quality of life, diabetes therapy, such as taking insulin or oral drugs can alter the quality of life either positively by lowering symptoms of higher blood sugar or negatively, by causing symptoms of lower blood sugar." (PMID 37491893, 2023). "In addition, when people with diabetes need to inject insulin, monitor their blood glucose, or take medications in public places, they often receive strange looks from others, which can lead to negative psychological experiences such as shame and stigma." (PMID 37620853, 2023). "However, in recent years, there has been a growth in experimental research associating BPA exposure to the pathophysiology of obesity, dysregulation of insulin and glucose signaling, and type 2 diabetes mellitus." (PMID 37175934, 2023). "In liver IPCs are detected as well in healthy, as in diabetic animals and/or under glucose load, and researchers consider that the conversion of hepatocytes into insulin-producing cells could be the basis of a new type of therapy for diabetes." (PMID 38019818, 2023). "In addition to continuous insulin supplementation, metformin is the main drug in the treatment of diabetes." (PMID 37195917, 2023). "Treatment with vitamin D has also been found to result in significant increases in insulin concentrations in rats with diabetes, which in turn could reduce hyperglycemia." (PMID 37569752, 2023). "These participants tended to be older, had lower levels of education, and included more APOE ε4 carriers; more of them had a baseline history of CVD, hypertension, insulin use, longer duration of diabetes, higher average HbA1c levels, and reported more depressive symptoms." (PMID 37457508, 2023).